MC4R (melanocortin 4 receptor)
Diseases named in the same sentence as MC4R in open-access papers (continued):
Sharing a sentence is not in itself a finding about the gene and the disease.
Obesity (continued). "The obesity genes MC4R, FTO and SH2B1 may participate in the central control of energy homeostasis." (PMID 19878575, 2009). "In summary, our findings indicate that setmelanotide treatment effectively activates PVN MC4R by upregulating the CaMKK2/AMPK pathways, thereby inhibit hyperphagia and reverse obesity in HO rats." (PMID 41601974, 2026). "Setmelanotide, an MC4R agonist, is FDA-approved for obesity due to rare genetic syndromes, including BBS, where it has shown significant improvement in appetite regulation and weight outcomes." (PMID 41333852, 2025). "Moreover, an MC4R agonist, setmelanotide (Set), which has a 20-fold MC4R selectivity compared with α-MSH, has been effective for weight loss in patients with the MC4R/POMC/leptin pathway polymorphism and has been approved by the FDA for treatment of obesity in these patients." (PMID 40232848, 2025). "It will be important to investigate whether MRAP2 variants affect multiple aspects of GPCR signaling, because inactivating mutations in MC4R that contribute to obesity may not affect canonical signaling but can affect internalization, homodimerization or other G protein pathways." (PMID 41401256, 2025). "Western diet (WD)-fed MC4R-KO mice and Gubra-Amylin non-alcoholic steatohepatitis (GAN) diet-fed mice models have been reported to highly resemble human MASH in terms of obesity, dyslipidemia, insulin resistance, liver injury, steatosis, and fibrosis." (PMID 41266634, 2025). "GWAS of SevO found numerous susceptibility loci that intersected with earlier-identified BMI loci including the archetypal FTO, MC4R, SH2B1 and NPC1 suggesting little etiological heterogeneity between obesity subgroups." (PMID 40939575, 2025). "Other NPY2R variants, such as rs12649641, rs2342676, and rs6857530, have additive effects with other significant obesity–depression genes (e.g., FTO and MC4R)." (PMID 41375608, 2025). "Setmelanotide, a melanocortin-4 receptor (MC4R) agonist, is FDA-approved for obesity related to BBS and has demonstrated significant improvements in appetite control and weight outcomes in clinical trials." (PMID 41333852, 2025). "Setmelanotide, a melanocortin-4 receptor (MC4R) agonist, is the first FDA-approved treatment targeting hypothalamic leptin-melanocortin pathway defects in monogenic obesity syndromes." (PMID 41393538, 2025). "Regarding CLOCK/CT, FTO/AT, GHRL/GT, LEP/GA, LEPR/AG, MC4R/CT we found intermediates values for weight, BMI, waist circumference, and WHR, reflecting moderate levels of body fat and obesity." (PMID 39203789, 2024). "For the obesity seen in ALMS and BBS, the MC4R agonist setmelanotide and GLP-1 receptor agonists (GLP-1 RAs) are promising therapeutic options." (PMID 39126056, 2024). "Another MC4R peptide agonist, the lipidized analog of α-MSH, called MC4-NN1-0182, was investigated in rats with diet-induced obesity (DIO) and DIO minipigs." (PMID 38577975, 2024). "Still, many data confirm the existence of pathogenic gene variants, e.g., Fat Mass and Obesity Associated Gene (FTO), beta-2-adrenergic receptor (ADRB2) gene, melanocortin-4 receptor (MC4R) and others with obesity." (PMID 38397196, 2024). "Chronically inhibiting PVN MC4R/PDYN neuron synaptic release by expressing tetanus toxin or ablating those neurons by expressing caspase-3 resulted in pronounced hyperphagia, obesity, and a significant elevation in food consumption." (PMID 38227343, 2024). "It is located in the transmembrane helix of the MC4R gene and is known to impair cyclic-AMP, leading to severe obesity." (PMID 38974580, 2024). "Conversely, MC4R antagonism or genetic disruption of MC4R causes hyperphagia, increased adiposity, insulin resistance and dyslipidemia without affecting BP, a finding that further confirms that insulin resistance and hyperinsulinemia are not the main drivers of obesity-induced hypertension." (PMID 38186879, 2024).
Obesity (continued). "Here, the authors show that the defence against overfeeding is preserved in obesity, and that it is independent from FGF21 and MC4R." (PMID 38331907, 2024). "This study investigates the relationship between six obesity-related genes (CLOCK, FTO, GHRL, LEP, LEPR, MC4R) and their impact on BMI, WC, HC, WHR, and emotional eating behavior in 220 Romanian adults." (PMID 39203789, 2024). "Perturbation of MC4R signaling in the PVH alone, or in both PVH and DMV results in hyperphagic obesity with reduced energy expenditure and defects in insulin sensitivity." (PMID 37443835, 2023). "Other mutations within the leptin–melanocortin pathway, such as in proopiomelanocortin (POMC), melanocortin receptor 4 (MC4R), brain-derived neurotrophic factor (BDNF), and the tyrosine kinase receptor B (NTRK2) genes, can also contribute to obesity." (PMID 37762850, 2023). "The mechanisms underlying the correlations of the rs17782313 polymorphism with obesity as well as hyperglycemia may be that this variant leads to abnormal expression of MC4R as it is located downstream of the MC4R gene without any amino acid alteration in MC4R receptor." (PMID 37621650, 2023). "Mice and humans with MC4R and SIM1 haplo-insufficiency develop hyperphagia, obesity and increased linear growth." (PMID 36175420, 2022). "However, high carbohydrate intake and MC4R rs17782313 were not risk factor for obesity (p ˃ 0.05)." (PMID 36123585, 2022). "Obesity and metabolism-related genotypes were also assessed by 10 studies, including FTO, UCP1, MC4R, and ADIPOQ." (PMID 36235756, 2022). "CREB mediates the effects of canonical MC4R signalling through the Gαs–cAMP–PKA cascade, and mice with genetic deletion of Creb1 in Sim1 neurons develop obesity, impaired thermogenesis, and reduced AVP expression." (PMID 36175420, 2022). "Therefore, the biased ligands for MC4R that selectively activate Gαq signaling to decrease food intake but not trigger Gαs signaling with cardiovascular side effects might be better drug candidates for obesity treatment." (PMID 36291616, 2022). "Similar to MC4R, MC3R was also identified as an important regulator of energy expenditure, with 7 DCVs [BMI SDS=3.3 (2.2)] showing early obesity, albeit with unclear difference between the number of carriers with and without obesity." (PMID 35574020, 2022). "It must be considered that despite the key role of MC4R in obesity, single mutations in MC4R might not be sufficient to significantly impact weight loss outcomes because of the contribution of other variants involved in polygenic obesity." (PMID 36553534, 2022). "Evaluated genotypes also included those relating to cardiovascular health (ACE), obesity and metabolism-related genotypes (FTO, UCP1, MC4R, and ADIPOQ), sweet taste perception (Tas1R2 and KCTD10), and endurance (GDF5)." (PMID 36235756, 2022). "The melanocortin-4-receptor (MC4R) binding affinity, internalization and receptor activation of α-MSH/IgG immune complex were also decreased in individuals with obesity." (PMID 35911732, 2022). "Aberrant hypomethylation of this gene causes ectopic expression of its protein, which binds to the melanocortin 4 receptor (MC4R) in the hypothalamus, disrupting its function and triggering hyperphagic obesity." (PMID 35163268, 2022). "MRAP2 potentiates MC4R signaling in vitro and the deletion of MC4R and MRAP2 both develop severe obesity in vivo." (PMID 35311242, 2022). "MC4R mutations that do not affect canonical Gαs protein-mediated signaling, previously considered to be non-pathogenic, nonetheless disrupt agonist-induced internalization, β-arrestin recruitment, and/or coupling to Gαs, establishing their causal role in severe obesity." (PMID 33761344, 2021). "AAV-Cre-mediated deletion of PVNMC4R leads to hyperphagia and obesity, while PVN-specific MC4R re-expression markedly suppresses hyperphagia and body weight gain in obese MC4R-null (MC4RloxTB/loxTB) mice." (PMID 34262481, 2021).
Obesity (continued). "MC4R mutant variant dysfunction may decrease ligand binding and expression of the receptor at the cell surface, with a reduction in MC4R agonist α-melanocyte-stimulating hormone (α-MSH)-induced cyclic adenosine monophosphate (cAMP) production, resulting in increased obesity and hyperphagia." (PMID 34835958, 2021). "Additionally, the melanocortin accessory protein MRAP2 has been shown to modulate trafficking and function of MC4R to a level that is physiologically significant, as transgenic mice with whole-body deletion and brain-specific deletion of Mrap2 develop severe obesity at a young age." (PMID 33761344, 2021). "The melanocortin-4 receptor (MC4R) is a member of the G-protein-coupled receptor (GPCR) superfamily, which has been extensively studied in obesity pathogenesis due to its critical role in regulating energy homeostasis." (PMID 33076233, 2020). "Their results showed that the effects of the GLP-1 RA liraglutide were independent of the MC4R pathway, suggesting that this could represent a therapeutic opportunity for patients with various forms of monogenic obesity, especially for those with MC4R mutation." (PMID 33261141, 2020). "The melanocortin-4 receptor (MC4R), highly expressed in the central nervous system (CNS), is one of the major factors in obesity pathogenesis." (PMID 33076233, 2020). "Indeed, obese individuals, carriers of different MC4R mutations, compared with obese and normal weight participants without these variants, were diagnosed with BED through the completion of a validated questionnaire, thus resulting in the co-existence between obesity and BED." (PMID 33202557, 2020). "We propose that regulation of MC4R activity by DNAJC27 enhances appetite through its effect on cAMP, thereby regulating obesity." (PMID 32733386, 2020). "Some genes from this group are the fat mass and obesity (FTO), melanocortin-4 receptor (MC4R), and the transmembrane protein 18 (TMEM18)." (PMID 33324496, 2020). "Our study pointed out the role of MC4R rs17782313 and ENPP1 rs1044498 genotypes in obesity determinisms in mothers and their newborns in correlation with BMI, MUAC, TST and bioimpedance parameters." (PMID 31350533, 2019). "Apolipoprotein A-I (apoA-I), melanocortin-4 receptor (MC4R)-specific agonist, GLP-1 dual and triple agonists, neuropeptides and prolactin-releasing peptide mimetics were specifically examined for their anti-obesity role." (PMID 30834248, 2019). "The genomic windows related to the slope for both traits also contain two growth-related genes, MC4R and LEP, both of which can regulate obesity and energy expenditure." (PMID 30760882, 2019). "It is already known that interactions between MC4R gene with diet play a significant role in obesity and T2DM development, but the mechanisms by which different variants of SNPs near MC4R gene may influence the metabolic changes that lead to obesity, have not been known particularly yet." (PMID 30945034, 2019). "Conversely, increased A2BP1 expression was found in obesity, Also, this gene interacted with ATXN2, INSR, and MC4R, which played important roles in metabolic pathways." (PMID 30547318, 2019). "Six novel variants were identified in five candidate genes in seven out of 105 children with severe obesity; two in SIM1 (p.W306C and p.Q36X), one in POMC (p.Y160H), one in PCSK1 (p.W130G fs Ter8), two in MC4R (p.D126E) and one in LEPR (p.Q4H)." (PMID 30991789, 2019). "Recently, other genes that are thought to have an impact in the development of obesity were discovered, such as: melanocortin receptor (MCR) MC4R, MC3R, MC2R, and also nucleotide pyrophosphatase/phosphodiesterase (ENPP1)." (PMID 31350533, 2019). "Consequently, MC4R agonists have been developed as potential therapeutics for obesity and have been proven effective in treatment of male and female sexual dysfunctions, whereas MC4R antagonists are potential anxiolytics that may function as antidepressants or for treating cancer-induced anorexia." (PMID 29910730, 2018).
Obesity (continued). "The relevance of NPY and its role, in combination with other regulatory peptides (POMC, AgRP, MC4-R and SOCS3), was clearly seen in adulthood, when obesity was settled in L-females." (PMID 29329236, 2018). "The anti‐obesity effect of the BRS‐3 agonist was still reportedly observed in Npy−/−, Mc4r−/−, Cb1r−/−, and Lepr−/− mice." (PMID 29568682, 2018). "Obesity develops as a result of inadequate production of α- and β-MSH, which normally activate the MC3R in the arcuate nucleus and the MC4R in the paraventricular nucleus and antagonize the action of agouti-related peptide (AgRP)." (PMID 28739551, 2018). "Our results indicate that high physical activity diminishes the obesity-promoting effect of FTO and MC4R." (PMID 28384342, 2017). "Consistent with this, studies in mice have shown that disruption of the MC4R, and specifically in the PVN, results in obesity as a result of hyperphagia and reduced energy expenditure, along with deteriorations in glucose homeostasis." (PMID 28592656, 2017). "In view of these effects, MC4R, which is a seven-transmembrane domain G-protein coupled receptor (GPCR), has been considered as a potential drug target for the treatment of obesity." (PMID 29031731, 2017). "In summary, in our sample of Chinese children, we replicated eight adult East Asian obesity-related loci (in/near FTO, MC4R, GNPDA2, PCSK1, SEC16B, MAP2K5, ITIH4 and BDNF) in the same direction of effect as previous reports in adults." (PMID 29212175, 2017). "Eight STRs flanking the MC4R gene—D18S851, D18S487, D18S69, D18S858, D18S849, D18S1155, D18S64, D18S38—have demonstrated linkage with obesity in Finnish sib pairs, with D18S849 showing the strongest linkage." (PMID 28615046, 2017). "These novel findings provide important evidence that adiponectin possibly mediates MC4R and BDNF involved in obesity." (PMID 28396685, 2017). "Severe early-onset obesity was observed in a girl with haploinsufficiency of SIM1, possibly acting upstream or downstream of MC4R (Holder, Butte & Zinn, 2000)." (PMID 25825681, 2015). "Together, these findings suggest potential opportunities for employing combination treatments that comprise parallel MC4R and GLP-1R agonism for the treatment of obesity and diabetes." (PMID 25652173, 2015). "For obesity, these include genes functioning in the leptin-melanocortin pathway, such as the leptin (LEP) and melanocortin 4 receptor (MC4R) genes." (PMID 26363598, 2015). "When selecting the SNPs to test, we aimed at choosing the ones mapping within or in proximity of well documented obesity genes (as FTO and MC4R, for instance) and as representative of the obesity status (both in terms of BMI and waist circumference)." (PMID 25890290, 2015). "In this regard, MC4R-KO mice, a unique rodent model of NASH accompanied by obesity and systemic insulin resistance, would be useful for evaluating the effectiveness of novel drugs to treat NASH." (PMID 25816330, 2015). "This is the first study to demonstrate significantly enhanced efficacy that results from combining MC4R and GLP-1R agonism for the treatment of obesity and diabetes." (PMID 25652173, 2015). "RM-493 is a small synthetic peptide with a unique activity profile distinct from other clinically tested MC4R agonists, including LY-2112688, and is currently in phase IIA clinical trials for the treatment of obesity and the metabolic syndrome." (PMID 25652173, 2015). "So far, several genes, such as proopiomelanocortin (POMC), leptin receptor (LEPR), leptin (LEP), proconvertase 1 (PC1), and melanocortin 4 receptor (MC4R), have been confirmed as the casual genes to the onset of monogenic obesity." (PMID 24707501, 2014). "Heterogeneity in effect sizes between class I/II and class III obesity was statistically significant only for FTO rs9939609 (Phet = 0.031) and borderline significant for MC4R rs17782313 (Phet = 0.050)." (PMID 23950976, 2013).
Obesity (continued). "Herein, we provide data from two mouse models, diet-induced obese (DIO) and melanocortin 4 receptor knockout mice (MC4R−/−;), which reveal that TSPO gene expression and protein density decrease in WAT and BAT as a function of obesity." (PMID 24260329, 2013). "It is well known that obese humans often have elevated levels of serum cholesterol which has also been observed in several mouse models of obesity including DIO rodents fed either a HFD or HFHC diet, as well as in MC4R−/− mice." (PMID 24260329, 2013). "Recently, many single nucleotide polymorphisms (SNPs) were identified by genome-wide association studies (GWASs) in adults and children with respect to the pathogenesis of obesity, including FTO, TMEM18, GNPDA2, INSIG2, MC4R, NEGR1, 1q25, BDNF and KCTD15." (PMID 24278475, 2013). "Obesity in Ay mice is believed to be a consequence of the agouti proteins serving as a constitutive antagonist of the melanocortin 3 receptor (MC3R) and melanocortin 4 receptor (MC4R) by mimicking the action of the agouti-related protein." (PMID 23418893, 2013). "Indeed, the initial GWAS with ∼14,000 subjects (Indian Asians and Europeans) and two GWAS in East Asians (∼150,000) have confirmed the significant association between MC4R polymorphism and BMI, although the association with obesity risk were not addressed among these three GWAS." (PMID 23049848, 2012). "The ovarian changes in the MC4R-/- mice discussed here are reminiscent of the polycystic ovary syndrome (PCOS), which frequently comes along with obesity." (PMID 19309531, 2009). "Furthermore, enhancing melanocortin signaling through overexpression of MC4R, POMC, or its derived peptides showed limited effects on obesity prevention or reversal." (PMID 40130157, 2025). "This study, employing multiple animal models, demonstrated that while chronic inhibition of POMC neurons or paraventricular MC4R-expressing neurons induced significant obesity, chronic activation of these neuronal populations failed to reduce body weight." (PMID 40130157, 2025). "In vivo, deletion of Mc4r from Kiss1 neurons in female mice replicates the reproductive impairments of Mc4r KO mice without inducing obesity." (PMID 40674128, 2025). "Although studies in rodents with diet-induced obesity treated with MC4R agonists have shown promising results, these results have not been observed in humans with obesity." (PMID 39929239, 2025). "These striking findings on the coupling of MC4R with Gq/11α and its effect on the IP1 response create new opportunities for research on MCRs related to obesity and signaling regulation that may lead to new therapeutic approaches." (PMID 40001512, 2025). "However, the MC4R agonist setmelanotide was recently FDA-approved, representing a significant advancement in the treatment of rare genetic forms of obesity." (PMID 40956393, 2025). "This study examined the relationship between appetite-regulating hormones and the expression of FTO and MC4R genes in the gastric tissue of patients with and without obesity." (PMID 41423640, 2025). "These obesity-related changes may include alterations in the leptin hormone which can stimulate POMC-expressing neurons and subsequently affect MC4R stimulation." (PMID 39542230, 2025). "Genes in the leptin–melanocortin pathway, such as leptin (LEP), leptin receptor (LEPR), melanocortin-4 receptor (MC4R), adenylyl cyclase 3 (ADCY3), and brain-derived neurotrophic factor (BDNF) genes, are established contributors to obesity and insulin resistance." (PMID 38674857, 2024). "The key genes involved in obesity are FTO, MC4R, LEP, LEPR or PPARG." (PMID 39769194, 2024). "Notably, individuals with the CLOCK (CC), FTO (AA), and LEP (AA) genotypes exhibited the highest BMI and WHR, while those with GHRL (TT), MC4R (CC), and LEPR (GG) genotypes, although showing lower values, were still correlated with overweight and obesity." (PMID 39203789, 2024).